TIMP2 (TIMP metallopeptidase inhibitor 2)
Diseases named in the same sentence as TIMP2 in open-access papers (continued):
Sharing a sentence is not in itself a finding about the gene and the disease.
breast carcinoma (continued). "The related protein TIMP2 is also important in breast cancer." (PMID 36768435, 2023). "Our study found statistically significantly lower serum levels of TGF-β1 and TIMP-2 in patients in the long-term follow-up period (>12 months) after breast cancer treatment than in healthy female volunteers, while the level of VEGFR-2 was comparable in these groups." (PMID 36136069, 2022). "Consistent with previous studies, decreased TIMP-2 expression may lead to myopia in mammals and did have an effect on breast cancer." (PMID 36430677, 2022). "Exosomal miR-4443 may also promote the metastasis of breast cancer cells through downregulating tissue inhibitors of metalloproteinase 2 (TIMP2) and upregulating several MMPs." (PMID 36230852, 2022). "Several studies have demonstrated tumor suppressive role of TIMP-2 in breast cancer." (PMID 36741729, 2022). "In conclusion, TIMP2 could be considered by a potential and promising target for novel therapeutics and biomarkers for breast cancer." (PMID 34678879, 2021). "The results showed that TIMP2 was down-regulated in various breast cancer subtypes." (PMID 34678879, 2021). "However, additional research is required to demonstrate our findings and motivate the clinical importance of TIMP2 in breast cancer." (PMID 34678879, 2021). "This research aims to evaluate the prognostic significance of TIMP2 in breast cancer treatment." (PMID 34678879, 2021). "High expression of TIMP-2 has been shown to correlate with adverse prognosis in breast cancer." (PMID 32984024, 2020). "TIMP-2 gene plays an important role in the development of breast cancer." (PMID 31088428, 2019). "Our findings identify a novel role for p95HER2-specific miRNA changes in distinguishing p95HER2 positive cancers from those overexpressing only HER2, and uncover a signaling axis from miR-221/222 and -503 over MYB proteins to TIMP2 important for controlling cell motility in breast cancer." (PMID 30833639, 2019). "Additionally, the UALCAN database demonstrated that the TIMP-2 gene was under-expressed in breast cancer tissues." (PMID 31088428, 2019). "In addition, earlier work in our laboratory suggests that TIMP2 delivers significant therapeutic benefits in murine lung and breast cancer models." (PMID 31882975, 2019). "Therefore, miR-4443 probably added to the chemoresistant capability of breast cancer cells by targeting TIMP2." (PMID 27504971, 2016). "Consequently, changes in TIMP2 mRNA and protein expression revealed that miR-4443 mimics suppressed expression of TIMP2 and induced migration in breast cancer cells." (PMID 27504971, 2016). "Mechanistic studies are needed to define the role of TIMP-2 in breast cancer seroma." (PMID 26361584, 2015). "In breast cancer, TIMP2 immunoexpression may be localized in cancer as well as stromal cells, however mRNA in situ hybridization indicates a lower TIMP2 synthesis in stromal cells than in tumour cells." (PMID 24229053, 2013). "However, elevated mRNA expression levels of TIMP-1 and TIMP-2 have been previously detected in breast cancer cell lines with high invasive and metastatic potential." (PMID 19144199, 2009). "In the present study, JS-K increased TIMP-2 levels in breast cancer cells." (PMID 18474097, 2008). "TIMP-2 has been shown to inhibit the invasiveness of breast cancer cells in vitro and in vivo." (PMID 18474097, 2008). "In this study, we have determined whether irradiation of a reconstituted basement membrane (Matrigel; Becton Dickinson, Bedford, MA, USA) could enhance the expression of MMP-2, MT1-MMP and TIMP-2 from breast cancer cells." (PMID 17987037, 2007). "This prompted us to test the hypothesis that the individual expression or the balance between MMP-2, MMP-14 and TIMP-2 expression may help to predict breast cancer prognosis." (PMID 16776850, 2006).
breast carcinoma (continued). "Of the MMP-14/TIMP-2/MMP-2 complex, MMP-14 was the factor most significantly associated with the outcome of breast cancer and was an independent factor of poor overall survival when adjusted for clinical prognostic factors, but not for certain ancillary markers." (PMID 16776850, 2006). "In the literature on breast cancer, the role of TIMP-2 was controversial." (PMID 16776850, 2006). "Thus, given the leading pathways of fibrogenesis in patients after breast cancer treatment, TIMP-2 may be a promising biomarker of fibrotic changes and a potential target for therapeutic agents." (PMID 36136069, 2022). "We could evaluate the importance of TIMP2 in breast cancer according to clinical characteristics." (PMID 34678879, 2021). "The failure of TIMP2 co-expressed gene patterns to discriminate lobular vs. ductal breast cancers, or squamous vs. adenocarcinomas in the lung may suggest that the 334 GOI profile reflects the host response in the tumor microenvironment (TME) rather than tumor autonomous gene expression patterns." (PMID 31882975, 2019). "Furthermore, high levels of TIMP-2 are correlated with adverse prognosis in breast cancer." (PMID 26361584, 2015). "Further, over-expression of TIMP2 in tumour stroma was associated with increased disease-free survival in prostate cancer, and down-regulation of MMP2 by TIMP2 over-expression reduced tumour growth and metastatic potential in a rat model of breast cancer-associated brain metastasis." (PMID 20041153, 2009). "Functional studies have demonstrated that CYP4Z1 overexpression promotes tumor angiogenesis in breast cancer through the regulation of VEGF-A and TIMP-2 expression, potentially mediated by PI3K and ERK1/2 activation." (PMID 39958347, 2025). "TGF-β1 mediates the mRNA and protein levels of MMPs (MMP-2 and MMP-9) and their inhibitors (TIMP-2 and RECK), which plays an essential role of extracellular matrix homeostasis control in breast cancer progression." (PMID 37248432, 2023). "In breast cancer, miR-4443 inhibits the expression of TIMP metallopeptidase inhibitor 2 (TIMP2) and phosphatidylethanolamine binding protein 1 (PEBP1), thereby promoting the metastasis and invasion of breast cancer." (PMID 36250718, 2022). "The intergroup analysis demonstrated that the patients after breast cancer treatment showed a decrease in the serum levels of TGF-β1 (U = 666, p < 0.001) and TIMP-2 (U = 637, p < 0.001) as compared to the group of healthy volunteers." (PMID 36136069, 2022). "However, the molecular mechanism had not been performed in breast cancer and we estimate that TIMP2 might be a diagnostic and potential therapeutic target for breast cancer even for other solid human cancers." (PMID 34678879, 2021). "Therefore, TIMP2 might be a newly identified diagnosis and prognosis molecular in breast cancer." (PMID 34678879, 2021). "Conversely, knockdown of TIMP2 showed a strong tendency to decrease migration and invasion in MCF-7, T47D, and SKBr-3 cells, with the magnitude of this effect varying between breast cancer cell lines." (PMID 30833639, 2019). "Similar to upregulation of p95HER2 and miR-221/222 and -503, knockdown of endogenous MYB family proteins increased TIMP2 mRNA (MCF-7 and p95HER2 MCF-7 cells) and protein (MCF-7, p95HER2 MCF-7, T47D, and SKBr-3 breast cancer cells) expression." (PMID 30833639, 2019). "Examination of 1097 breast cancer tissues and 114 normal tissues from The Cancer Genome Atlas (TCGA) using the UALCAN database demonstrated that TIMP-2 was under-expressed in breast cancer tissues." (PMID 31088428, 2019). "So we further assessed TIMP2 mRNA and protein expressions in MDA-MB-231 breast cancer cells affected by abnormal expression of miR-4443." (PMID 27504971, 2016). "In particular, IFNγ, leptin, TGFβ1, TIMP1, TIMP2, thrombopoietin and VEGF levels were significantly inhibited by anandamide in the conditioned medium of MDA-MB-231 breast cancer cells." (PMID 25147760, 2014).
breast carcinoma (continued). "TIMP-2 is a main negative regulator of MMP-2 enzyme activity and involved in several tumor metastasis processes, including breast cancer." (PMID 23533649, 2013). "We performed gelatin zymography to measure the MMP-2 and MMP-9 activities and Western blot to examine the TIMP-1, TIMP-2, MMP-2 and MMP-9 expressions in breast cancer cells." (PMID 23533649, 2013). "For this reason, we first analyzed the mRNA expression levels of MMP-2, MMP-9, MMP-14, TIMP-1, TIMP-2, TIMP-3 and RECK, in the same panel of five human breast cancer cell lines, but now maintained in culture until achieving 80-90% confluence." (PMID 22260435, 2012). "Taken together, the results obtained demonstrate that TGF-β1 is a common regulator of MMPs (MMP-2 and MMP-9) and their inhibitors (TIMP-2 and RECK) in breast cancer cell models." (PMID 22260435, 2012). "Evaluation of the activities of TIMP-1, TIMP-2 and TIMP-3 in canine mammary tumor samples by reverse zymography has shown that low activity can be correlated with a malignant phenotype." (PMID 21726449, 2011). "Studies of canine mammary tumors suggest that pro-MMP-2 activation requires the formation of a ternary complex that consists of the C-terminal domain of pro-MMP-2, TIMP-2 and MT1-MMP." (PMID 21726449, 2011). "Conversely, experimental inhibition of PRDX6 expression decreased the invasive and potential potential of breast cancer cells, partially through regulation of uPAR, Ets-1, MMP-9, RhoC and TIMP-2 expression." (PMID 17980029, 2007). "All these results indicate that PRDX6 promotes breast cancer progression, partially through upregulation of uPAR, Ets-1, MMP-9 and RhoC expression and downregulation of TIMP-2 expression." (PMID 17980029, 2007). "Overexpression of peroxiredoxin 6 leads to a more invasive phenotype and metastatic potential in human breast cancer, at least in part, through regulation of the levels of uPAR, Ets-1, MMP-9, RhoC and TIMP-2 expression." (PMID 17980029, 2007). "Matrix metalloproteinase-1 was immunohistochemically detected in 88.3% of breast carcinomas, MMP-2 in 42%, MMP-7 in 87.4%, MMP-9 in 74%, MMP-11 in 89.3%, MMP-13 in 73.3%, MMP-14 in 90%, TIMP-1 in 95%, TIMP-2 in 87% and TIMP-3 in 82.3%." (PMID 17848954, 2007). "In the present study, we demonstrated that the enhancement of invasive phenotype of breast cancer cells by PRDX6 was accompanied by upregulation of MMP-9 and Ets-1 expression and downregulation of TIMP-2 expression." (PMID 17980029, 2007). "In our tumor bank, information for MMP-2 was available from 610 breast cancers, from 544 for MMP-14 and from 549 cases for TIMP-2." (PMID 16776850, 2006). "Monocyte MMP-2 enzymatic activity and MMP-2 as well as TIMP-1 and TIMP-2 protein levels were increased in response to soluble factors from MCF-7 and MDA-MB-231 breast cancer cells." (PMID 16168111, 2005). "Moreover, the expression of metastasis‐suppressing genes, including MTSS1, TIMP2, Rb1, and PTEN, gradually increased with increasing Arid4a expression in human breast cancer samples." (PMID 40066676, 2025). "Comprehensive survival analysis of stromal ILC genes in human breast cancer datasets identified a positive association with improved survival and PAPPA and TIMP2 (tissue inhibitor of metalloproteinase 2) in ILC but not IDC." (PMID 35205651, 2022). "TGF-β1, TIMP-2, and VEGFR-2 have been recognized in a number of studies as the key regulators of fibrogenesis and angiogenesis, which determined the choice of these biomarkers for detecting the effects of breast cancer treatment." (PMID 36136069, 2022). "Furthermore, the treatment of MCF-7 human breast cancer cells with ATRA, resulted in substantial inhibition of the expression and activity of the pro-MMP2 enzyme as well as a significant induction in TIMP2 protein expression." (PMID 36135009, 2022). "In prostate and breast cancers, TET1 transactivates TIMP2 and TIMP3 to inhibit cancer invasion." (PMID 35805009, 2022).
breast carcinoma (continued). "It was also found that the type of treatment, the presence of lymphedema, shoulder joint contracture, and changes in lymphoscintigraphy did not affect the levels of TGF-β1, VEGFR-2, and TIMP-2 within the group of patients after breast cancer treatment." (PMID 36136069, 2022). "TIMP2 was previously found as a matrix metalloproteinase (MMP) inhibitor that restrained cell proliferation and metastasis in GC and breast cancer." (PMID 34692770, 2021). "Finally, using miR mimic overexpression and TIMP2 siRNA knockdown, we show that a miR-221/222, miR-503 → MYB, MYBL1 → TIMP2 axis stimulates migration and invasion of MCF-7 breast cancer cells." (PMID 30833639, 2019). "As expected, a significant positive correlation was found between the secretion of u-PA and MMPs and a significant negative correlation between u-PA and TIMP-2 secretion by NM treatment of breast cancer cells." (PMID 22736175, 2012). "In this in vitro study, the NM significantly inhibited breast cancer cell lines MDA-MB-231 and MCF-7 and uterine cell line SK-UT-1 secretion of u-PA and MMP-9 and increased their secretion of TIMP-2, suggesting its potential in modulating breast and uterine cancer invasion and metastasis." (PMID 22736175, 2012). "Here, we proposed a more extensive approach by analyzing the mRNA expression levels of different MMPs (MMP-2, MMP-9 and MMP-14) and MMP inhibitors by qRT-PCR (TIMP-1, TIMP-2 and RECK) in several models (five human breast cancer cell lines, 72 primary breast tumors and 30 adjacent normal tissues)." (PMID 19144199, 2009). "We analyzed the expression levels of MMP-2, MMP-9 and MMP-14 and their inhibitors (TIMP-1, TIMP-2 and RECK) by quantitative RT-PCR (qRT-PCR) in five human breast cancer cell lines presenting increased invasiveness and metastatic potential, 72 primary breast tumors and 30 adjacent normal tissues." (PMID 19144199, 2009). "Moreover, all analyzed MMPs inhibitor (TIMP-1, TIMP-2 and RECK) are also over-expressed in MDA-MB-435, MDA-MB-231 and Hs578T breast cancer cells." (PMID 19144199, 2009). "Here, we propose a more comprehensive approach by analyzing the expression levels of several MMPs (MMP-2, MMP-9 and MMP-14) and MMP inhibitors (TIMP-1, TIMP-2 and RECK) in different models (five human breast cancer cell lines, 72 primary breast tumors and 30 adjacent normal tissues)." (PMID 19144199, 2009). "This inhibitory effect of ATRA on MMP-2 activity in human breast cancer cells (MCF-7) may result due to its inhibitory effect on MT1-MMP, EMMPRIN, and upregulation of TIMP-2." (PMID 19636436, 2009). "ProMMP-2 is activated on the surface of breast cancer cells by the MT1-MMP and TIMP-2." (PMID 17987037, 2007). "Low TIMP-2 levels in the blood of breast carcinoma patients could indicate more activated MMP-2 and therefore higher usage of TIMP-2, or alternatively, the lower levels could be due to lower production of TIMP-2, leading to lesser inhibition of MMP-2 activity." (PMID 19662197, 2007). "MMP-2, MMP-14 and TIMP-2 expression has been evaluated by 35S mRNA in situ hybridization on paraffin material of 539 breast cancers without distant metastasis at diagnosis and with a median follow-up of 9.2 years." (PMID 16776850, 2006). "In the present article we report the novel findings that JS-K inhibits the invasive activity of breast cancer cells across the Matrigel basement membrane at doses by which JS-K was not cytotoxic, and that increasing TIMP-2 production is one mechanism by which JS-K mediates its anti-invasive effects." (PMID 18474097, 2008). "Accordingly, it has been reported that several other MMPs and TIMPs may be overexpressed and/or related to clinical outcome in breast cancer, such as MMP-11 MT1-MMP (MMP-14) MMP-13, TIMP-1 or TIMP-2." (PMID 17848954, 2007). "However, the expression patterns and exact roles of TIMP2 had not been elucidated in breast cancer." (PMID 34678879, 2021).
breast carcinoma (continued). "Five genes (MMP3, CDKN1A, RUNX1, TIMP2, CCND1) are common in cervical, ovarian, endometrial cancers, but not in breast cancer." (PMID 31205821, 2019). "In 2D culture, breast cancer cells expressing high levels of MT1-MMP were capable of widespread ECM degradation and TIMP-2-mediated proMMP-2 activation, but were not the most migratory." (PMID 27756325, 2016). "Additionally, although abnormally high levels of MT1-MMP overexpression may not reflect those seen in primary breast cancers, there is still mechanistic value in this approach, as utilized in this study to demonstrate the constancy of the TIMP-2 mediated activation of proMMP-2 by MT1-MMP." (PMID 27756325, 2016). "Of the eight cytokines that were differentially expressed between seroma fluid from breast cancer and non-cancer patients, three were specifically up-regulated in malignant seroma fluid (GRO, ENA-78/CXCL5 and TIMP-2)." (PMID 26361584, 2015). "Thus, it can be assumed that the TIMP-2 and TGF-β1 pathways are not crucial in maintaining and progressing fibrosis in patients after radical breast cancer treatment in the long-term follow-up period of >12 months." (PMID 36136069, 2022). "The miR-221/222/503 – MYB/MYBL1 - TIMP2 – cell motility axis was recapitulated in both T47D cells (Luminal A subtype) and SKBr-3 cells (HER2-positive subtype), suggesting a the signaling axis is universal rather than cell line/breast cancer subtype specific." (PMID 30833639, 2019). "However, clinical studies on breast cancer are rare, limited in size and do not address the potential interaction of all three factors (MMP-2, MMP-14 and TIMP-2)." (PMID 16776850, 2006).